PTPN2 (protein tyrosine phosphatase non-receptor type 2)
Diseases named in the same sentence as PTPN2 in open-access papers (continued):
Sharing a sentence is not in itself a finding about the gene and the disease.
glioma (continued). "We observed that PTPN2 transcript levels increased with the glioma grade and were associated with IDH wild-type gliomas and the mesenchymal subtype of GBM." (PMID 29764444, 2018). "There was a close correlation between PTPN2 and the immune response and inflammatory activity in gliomas." (PMID 29764444, 2018). "Owing to tumor heterogeneity in the different grades of glioma, the prognostic value of PTPN2 expression was also investigated in GBM." (PMID 29764444, 2018). "To explore the main biological signatures of PTPN2 in glioma, we investigated the related genes by the Pearson correlation analysis (|r| > 0.6 and p < 0.05)." (PMID 29764444, 2018). "The results show that the transcript levels of PTPN2 were decreased in gliomas with MGMT promoter methylation in both CGGA (p = 0.013) and TCGA (p < 0.001) datasets." (PMID 29764444, 2018). "We constructed a risk model using HOXA5, PTPN2, WT1, HOXD10, POSTN, ADAMDEC1 and MYBPH expression data from a cohort of patients in TCGA, and found that it had significant prognostic value for ATRX-wt glioma patients." (PMID 37812190, 2023). "Furthermore, PTPN2 deletion in human glioblastoma T98G cells was observed to prevent colony formation and induce apoptosis, demonstrating that PTPN2 was required for glioma growth." (PMID 36968224, 2023). "PTPN1 and PTPN2 can be used as predictors of poor prognosis in glioma patients." (PMID 35957898, 2022). "Our results highlight PTPN2 as a novel immunotherapy target in glioma, which could also amplify the therapeutic efficacy when combined with other ICIs." (PMID 29764444, 2018). "In this study, we characterized PTPN2 mRNA levels in 996 patients with glioma." (PMID 29764444, 2018). "Therefore, we utilized the Chinese Glioma Genome Atlas (CGGA) dataset, which consists of 325 glioma samples, to investigate PTPN2 in gliomas." (PMID 29764444, 2018). "Thus, it will be necessary to study PTPN2 protein levels to confirm the crucial role of PTPN2 in gliomas." (PMID 29764444, 2018). "Furthermore, another study observed this phenomenon, indicating that oxidative stress may be exploited to stimulate PTPN2 inactivation for treating gliomas." (PMID 35935861, 2022). "Thus, PTPN2 is an indicator of worse overall survival in patients with gliomas and glioblastomas." (PMID 36077422, 2022). "Moreover, our results proved the prognostic value of PTPN2 both for patients with glioma and GBM." (PMID 29764444, 2018). "We found a higher infiltration of antitumor immune cells (CD8+ T cells, TAMs, and NK cells) in gliomas with high PTPN2 expression, which is not in agreement with a previous study that reports a significant increase in the number of CD8α+ cells in PTPN2-deficient tumors." (PMID 29764444, 2018). "Immune-related pathways such as TNF signalling (IDH3B/G, MDH1, ACO2, SDHA, OGDHL) and JAK/STAT3 (PIAS2/3, PTPN2, AKT1/2, MCL1, CISH, AOX1) signalling are enriched in gliomas and play a critical role in their progression." (PMID 41007296, 2025). "PTPN2 is oxidized and inactivated by H2O2 and the expression levels of PTPN2 are increased in GBM and isocitrate dehydrogenase (IDH) wild-type gliomas." (PMID 35935861, 2022). "PTPN2 transcript level is grade-dependent and significantly increased in isocitrate dehydrogenase (IDH) wild-type and mesenchymal subtype gliomas." (PMID 36077422, 2022). "In the CGGA cohort, glioblastoma (GBM) showed higher levels of PTPN2 than grade II and grade III gliomas (Student’s t test, p < 0.001 and 0.030, respectively)." (PMID 29764444, 2018). "In conclusion, our study revealed that an immune signature based on HOXA5, PTPN2, WT1, HOXD10, POSTN, ADAMDEC1 and MYBPH expression effectively predicted the prognosis of ATRX-wt glioma patients, and demonstrated that immunotherapy was effective for low-risk patients." (PMID 37812190, 2023).
glioma (continued). "A receiver operating characteristic curve analysis indicated that HOXA5, PTPN2, WT1, HOXD10, POSTN, ADAMDEC1 and MYBPH had significant prognostic value for the survival of ATRX-wt glioma patients (AUC = 0.84, 0.81, 0.79, 0.91, 0.80, 0.79 and 0.85, respectively)." (PMID 37812190, 2023). "Glioma grade, IDH status, PTPN2 expression, and metagenes of patients were visualized as heat maps." (PMID 29764444, 2018). "However, the difference in PTPN2 levels between grade II and grade III gliomas was modest in the CGGA cohort (p = 0.0497)." (PMID 29764444, 2018). "Unfortunately, there is no comprehensive report on PTPN2 in gliomas." (PMID 29764444, 2018). "As PTPN2 plays a negative role in antitumor immunity, it might affect the survival of patients with glioma." (PMID 29764444, 2018).
Insulin resistance (11 papers, 2016 to 2025). Increased resistance towards insulin, that is, diminished effectiveness of insulin in reducing blood glucose levels. "In the liver, PTPN2 deficiency results in enhancement of the signaling of growth hormone, insulin resistance, increased weight and hepatic steatosis." (PMID 41019340, 2025). "G6pdx, Ptpn2, Lepr, and Kras, which are involved in insulin resistance, are regulated by different miRNAs." (PMID 39823117, 2025). "PTPN2 reduces insulin resistance by inhibiting the inflammatory response of cells and the body and then plays a role in regulating the lipid metabolism disorder of the body, so it can be used as a therapeutic target for reducing atherosclerosis." (PMID 37670950, 2023). "Knockout of PTPN2 in apoE−/− mice leads to severe insulin resistance, and then leads to disordered lipid metabolism and atherosclerosis." (PMID 37670950, 2023). "Since PTPs relevant to insulin resistance are promising antidiabetic targets, the identification of PTPN2 and PTPN6 inhibitors could be an effective strategy for treating or preventing type 2 diabetes." (PMID 37374154, 2023). "In a mouse model combining hyperglycaemia and hypercholesterolaemia (streptozotocin diabetic, ApoE‐/‐ mice), mice showed severe insulin resistance, renal dysfunction, micro‐inflammation, subsequent extracellular matrix expansion and decreased expression of PTPN2." (PMID 30955247, 2019). "Several protein tyrosine phosphatases (PTPs), particularly PTPN1, PTPN2, PTPN6, PTPN9, PTPN11, PTPRS, and DUSP9, are involved in insulin resistance." (PMID 37374154, 2023). "Overexpression of PTPN2 significantly reduces the levels of NF-κB, TNF-α, IL-6, and the inflammatory response in diabetic mice, and then alleviated insulin resistance." (PMID 37670950, 2023).
skin cancer (10 papers, 2010 to 2025). "In mice, the conditional deletion of Ptpn2 can also contribute to the development of skin cancers, as well as hepatocellular carcinomas, due to the promotion of STAT3 signalling." (PMID 34884538, 2021). "The relation between PTPN2 and Akt has been demonstrated in other cancer types as well, like skin cancer and lung cancer." (PMID 31025094, 2019).
type 2 diabetes (10 papers, 2014 to 2025). "Taken together, our results suggest that methyl syringate, a dual-targeting inhibitor of PTPN2 and PTPN6, is a promising therapeutic candidate for the treatment or prevention of type 2 diabetes." (PMID 37374154, 2023). "In conclusion, our results suggest that methyl syringate, a dual-targeting inhibitor of PTPN2 and PTPN6, exhibits antidiabetic effects and can be used as a functional food ingredient or pharmaceutical supplement to prevent type 2 diabetes." (PMID 37374154, 2023). "Several PTPs, such as PTPN1, PTPN2, PTPN9, PTPN11, PTPRS, and DUSP9, disrupt insulin signaling and trigger type 2 diabetes, indicating that PTPs are promising drug targets for the treatment or prevention of type 2 diabetes." (PMID 35204821, 2022). "As PTPN2 and PTPN6 have been shown to negatively regulate insulin action, the identification of inhibitors of these proteins is considered an effective strategy for the treatment or prevention of type 2 diabetes." (PMID 37374154, 2023). "Diverse PTPs, such as PTPN1, PTPN2, PTPN9, PTPN11, PTPRS, and DUSP9, have been reported to attenuate insulin signaling and trigger type 2 diabetes, indicating that PTPs are promising drug targets for the treatment or prevention of type 2 diabetes." (PMID 35204821, 2022). "Some PTPs, such as PTPN1, PTPN2, PTPN9, PTPN11, PTPRS, and DUSP9, have been shown to attenuate insulin signaling and trigger type 2 diabetes, indicating that PTPs are promising drug targets for the treatment or prevention of type 2 diabetes." (PMID 35204821, 2022). "Therefore, the identification of dual-targeting inhibitors of PTPN2 and PTPN6 could be a potential therapeutic strategy for the treatment or prevention of type 2 diabetes." (PMID 37374154, 2023).
colorectal cancer (9 papers, 2020 to 2026). A primary or metastatic malignant neoplasm that affects the colon or rectum. "Moreover, one study has demonstrated that myeloid cell-specific loss of Ptpn2 promotes inflammasome activation, resulting in protection from colorectal cancer." (PMID 33122197, 2020). "Similarly, high expression of PTPN2 is implicated in the incidence of colorectal cancer, and specific deletion of PTPN2 in bone marrow cells and macrophages prevents the development of colorectal cancer, although it promotes inflammation in the intestine." (PMID 35957898, 2022). "In colorectal cancers, PTPN2 and MET have also been recognized as modulators of JAK1/2 phosphorylation, thereby affecting the signaling of the pathway." (PMID 40909948, 2025). "Additionally, PTPN2 deletion in T cells enhances the efficacy of anti-PD-1 therapy and achieves complete tumor clearance in a murine colorectal cancer model." (PMID 36077422, 2022). "Moreover, PTPN2 positively regulated mitochondrial respiration in HCT116 human colorectal cancer cells via STAT3 phosphorylation." (PMID 36077422, 2022). "Colorectal cancer remains a major clinical challenge, and dual targeting of PTPN1 and PTPN2 represents a promising strategy to modulate conserved phosphatase signaling relevant to tumor biology and immune regulation." (PMID 42079868, 2026). "For stomach adenocarcinoma (STAD) and colorectal cancer (CRC), PTPN2 expression levels are correlated with cancer incidence." (PMID 36077422, 2022). "For colorectal cancer (CRC), PTPN2, PTPN21 and PTPN22 levels were correlated with incidence; expression of PTPN5, PTPN12, and PTPN14 was correlated with TNM stage and N stage; high PTPN5 or PTPN7 expression was associated with increased hazards of death." (PMID 32536826, 2020). "In colorectal cancer, PTPN1, PTPN2 and PTPN18 undoubtedly drive its progression." (PMID 35957898, 2022). "CCLE analyses showed that in esophagus cancer cell lines, PTPN1, PTPN4 and PTPN12 were highly expressed; in gastric cancer cell lines, PTPN2 and PTPN12 were highly expressed; in colorectal cancer cell lines, PTPN12 was highly expressed while PTPN22 was downregulated." (PMID 32536826, 2020).
glioblastoma (9 papers, 2008 to 2024). The most malignant astrocytic tumor (WHO grade IV). "PTPN2 is overexpressed in glioblastoma and its expression associates with IDH wild–type expression and the mesenchymal subtype that indicates a worse prognosis." (PMID 34532286, 2021). "Notably, the inhibition of PTPN2 has been observed to impede the proliferation of glioblastoma multiforme (GBM)." (PMID 38214842, 2024). "Furthermore, there is an inverse relationship between PTPN2 and an inflammatory response in glioblastoma." (PMID 34532286, 2021). "TC45, a 45-kDa variant of PTPN2, has the potential to dephosphorylate Delta EGFR, which is the most common mutation of the EGFR gene and promotes glioblastoma multiforme (GBM) growth." (PMID 36077422, 2022). "Thus, we believe that a PTPN2 siRNA–tumor–specific aptamer therapeutic may provide an important strategy to overcome ICB resistance of glioblastoma patients." (PMID 34532286, 2021). "Likewise, PTPN2 and PTPN3 are correlated with poor patient prognosis in glioblastoma (GBM)." (PMID 35957898, 2022).
T-cell acute lymphoblastic leukemia (8 papers, 2017 to 2023). Acute lymphoblastic leukemia of T-cell origin. "Two cases (PD40822 and PD40836) involved clonal frameshifts in genes associated with T-cell ALL (PTPN2 p.A108fs∗5 and WT1 p.V371fs∗14, respectively)." (PMID 36867579, 2023). "In terms of cancer, recent studies revealed a focal deletion of PTPN2 in human T-cell acute lymphoblastic leukemia, implying the potential role of TC-PTP as a tumor suppressor." (PMID 29207596, 2017). "Kleppe and colleagues demonstrated that PTPN2 regulates T-cell proliferation via JAK/STAT signaling in patients with T-cell acute lymphoblastic leukemia (T-ALL), and they hypothesized that PTPN2 expression correlates with tumor response to the tyrosine kinase inhibitor imatinib." (PMID 36968224, 2023).
hepatocellular carcinoma (7 papers, 2020 to 2025). A malignant tumor that arises from hepatocytes. "Deficiency of PTPN2 in hepatocytes resulted in maladjustment of signal transduction and activation of transcription 1 (STAT1) and STAT3, which eventually accelerated the progression on the spectrum of steatosis-NASH-cirrhosis-hepatocellular carcinoma (HCC) in mice." (PMID 35269812, 2022). "In hepatocellular carcinoma, lncRNA TINCR interacts directly with and inhibits PTPN2 to promote the proliferation and invasion through activating STAT3 signaling." (PMID 35957898, 2022). "The oxidative hepatic environment in obesity induces PTPN2 inactivation and the resultant enhanced STAT1 and STAT3 signaling, which promotes T cell recruitment and ensures non-alcoholic steatohepatitis and fibrosis, as well as hepatocellular carcinoma." (PMID 36077422, 2022).
lung carcinoma (7 papers, 2016 to 2025). "Second, although we demonstrated the association of thetwo novel potentially functional loci in PTPN2 with lung cancer risk with functional evidence from eQTL analyses, the exact biochemical and molecular mechanisms are still unclear." (PMID 28400551, 2017). "We performed an overall meta-analysis to evaluate associations between the two PTPN2 SNPs and lung cancer risk." (PMID 28400551, 2017). "Taken together, the present study revealed two novel, potentially functional susceptibility loci in PTPN2 associated with lung cancer risk in European populations, particularly among ever smokers and squamous carcinoma." (PMID 28400551, 2017). "PTPN2 pathway is involved in the risk factors and survival of lung cancer." (PMID 36077422, 2022). "The principal findings included two novel, potentially functional SNPs, rs2847297 and rs2847282 of PTPN2, that were both associated with a decreased lung cancer risk and a decreased mRNA expression level of PTPN2, particularly in subgroups of ever smokers and squamous cell lung carcinoma." (PMID 28400551, 2017). "In conclusion, the PTPN2 rs2847297 and rs2847282 may be potential susceptible loci for lung cancer risk." (PMID 28400551, 2017). "Moreover, PTPN2 and its-linked network are associated with lung cancer metastasis." (PMID 36077422, 2022). "After multiple-testing correction, 112 SNPs in eight genes (ATR, EGFR, MET, PIK3R1, PIK3R3, PTPN2, STAT3, and STAT5A) remained significantly associated with lung cancer risk with FDR <0.20." (PMID 28400551, 2017). "We found that PTPN2 mRNA expression levels in matched lung cancer tissues were increased compared to adjacent normal tissues from the TCGA database, some other studies also demonstrated that PTPN2 expression levels were higher in lung AD28, 29 and SQ30, 31 than in normal lung tissues." (PMID 28400551, 2017). "Thus, PTPN2‐deficient CAR T cells might be especially effective against tumours such as oestrogen receptor‐negative and triple‐negative breast cancers or lung cancers that have low PTPN2 levels." (PMID 31803974, 2020).
psoriasis (7 papers, 2011 to 2024). An autoimmune condition characterized by red, well-delineated plaques with silvery scales that are usually on the extensor surfaces and scalp. "For example, rs2816316 on near RGS1 exhibits evidence of association to MS; rs2542151 and rs1893217 on near PTPN2 has modest association to psoriasis." (PMID 21852963, 2011). "Furthermore, our results show that the genes mediating the development of IBD in psoriasis may be associated with the following genes CSF2RA/SOCS1/PTPN2/STAT3/IL21R, which has implications for the exploration of co-morbid targets in PsO combined with IBD." (PMID 38803495, 2024).
anemia (6 papers, 2012 to 2025). A reduction in the number of red blood cells, the amount of hemoglobin, and/or the volume of packed red blood cells. "Loss of Ptpn2 in mice caused features of anemia, including iron deficiency associated with reduced apical membrane expression of DMT1." (PMID 40244226, 2025). "Collectively, these data indicate that Ptpn2-deficient mice have features of anemia and can be utilized as an experimental model to study mechanisms of iron deficiency upon loss of (functional) PTPN2." (PMID 40244226, 2025). "Ptpn2-KO mice showed characteristics of anemia, including reduced hemoglobin concentrations along with serum and tissue iron deficiency and elevated serum hepcidin levels vs. Ptpn2-WT and Het mice." (PMID 40244226, 2025). "In differentiating the type of anemia, the mean corpuscular volume (MCV) of erythrocytes was reduced in Ptpn2-KO mice, consistent with iron deficiency anemia." (PMID 40244226, 2025). "TC-PTP-deficient (Ptpn2−/−) mice develop thymus atrophy and succumb to anemia and progressive systemic inflammatory disease within the first 2 weeks of birth." (PMID 30208623, 2018). "Ptpn2−/− (BALB/c-129SJ) mice develop severe anemia by 21 days of age associated with defective bone marrow erythropoiesis." (PMID 22590589, 2012). "Furthermore, Ptpn2-KO mice have profound splenomegaly, which is correlated with the severity of iron deficiency anemia." (PMID 40244226, 2025). "Given the marked defects in serum iron levels and features of anemia we observed in whole-body Ptpn2-deficient mice, we investigated whether Ptpn2-KO mice have diminished tissue iron levels." (PMID 40244226, 2025). "Interestingly, serum hepcidin levels were elevated in Ptpn2-deficient mice, a feature that is frequently present in anemia of chronic disease (ACD)." (PMID 40244226, 2025). "Together, these data demonstrate that constitutive Ptpn2 deficiency in mice results in alterations of iron handling genes in duodenal enterocytes and serum hepcidin concentrations, which may contribute to the iron deficiency and the manifestation of anemia." (PMID 40244226, 2025). "We confirmed that constitutive whole-body Ptpn2-KO mice exhibit features of anemia, including reduced hemoglobin concentrations accompanied by serum and tissue iron deficiency." (PMID 40244226, 2025). "Regarding the type of anemia present, the mean corpuscular volume (MCV) of erythrocytes was decreased in Ptpn2-deficient mice, consistent with the features of IDA compared to ACD where MCV should be unaltered." (PMID 40244226, 2025). "Additionally, Ptpn2-deficient mice have reduced hematocrit levels and hemoglobin concentrations—detected by CBC analyses—thus supporting the presence of anemia." (PMID 40244226, 2025). "Furthermore, automated CBC revealed that these Ptpn2-KO mice have reduced hematocrit levels and hemoglobin concentrations, suggesting the presence of anemia." (PMID 40244226, 2025). "Ptpn2−/− (BALB/c-129SJ) mice exhibit defects in hematopoiesis, in particular in B cell development and erythropoiesis and develop severe anemia." (PMID 22590589, 2012).